ITGB1 (integrin subunit beta 1)
Diseases named in the same sentence as ITGB1 in open-access papers (continued):
Sharing a sentence is not in itself a finding about the gene and the disease.
cancer (continued). "Recently, the direct interaction was shown to involve integrin-α5β1 (ITGA5/ITGB1) on cancer cells and fibronectin assembled on the surface of CAFs." (PMID 36936987, 2023). "We also explored the potential compounds in treating the ITGB1 high expressed DGC tumors by using the Genomics of Drug Sensitivity in Cancer (GDSC) database and Profiling Relative Inhibition Simultaneously in Mixtures (PRISM) database." (PMID 37007126, 2023). "ITGB1 has been found to be the receptor of fibronectin (FN), collagen, laminin, etc. and has been shown to regulate the invasion and metastasis in several cancer types." (PMID 36997926, 2023). "The results of IHC also proved that ITGB1 was highly expressed in CC tissue, compared with non-cancer tissues." (PMID 37449209, 2023). "This study focused mainly on ITGB1, given its established role in the regulation of several major hallmarks of cancer." (PMID 36968231, 2023). "Experimentation using ITGB1 knock-out cells supported this analysis and notably confirmed the relationship between strand tapering and cancer cell-ECM adhesion." (PMID 36892272, 2023). "Our results however revealed that YAP1 is transcriptionally activated through an ITGA5/ITGB1/CREB pathway after interaction with fibroblasts in cancer cells." (PMID 36936987, 2023). "We observed a significant downregulation of ITGB4 in dormant as compared to the proliferating cancer cells in vivo, and in 2-DG-treated as compared to vehicle-treated cancer cells in vitro, while the expression of ITGB1 was unaltered." (PMID 37456245, 2023). "ITGB1, a subunit of the integrin family, is aberrantly overexpressed in solid tumors and is related to the poor prognosis of diverse cancers." (PMID 36760719, 2023). "Positive ITGB1 protein expression was detected in 77.9% (148/190) of intestinal‐type cancers, 40.7% (59/145) of diffuse‐type cancers, 53.1% (34/64) of mixed‐type cancers, and 77.8% (14/18) of indeterminate‐type cancers." (PMID 35864742, 2023). "ITGB1 is highly expressed in many malignant tumors, while studies have confirmed correlations between the level of ITGB1 expression and the degree of differentiation, invasion, and lymphatic metastasis in GC." (PMID 37667169, 2023). "Of those mediators, long noncoding RNA or microRNA can initiate and activate cancer development by ITGB1/FAK/PI3K/AKT signals." (PMID 37855260, 2023). "Together, these results demonstrate that ZEB1/YAP1 axis in cancer cells potentially functions downstream of ITGA5/ITGB1 interaction with fibronectin on the surface of fibroblasts." (PMID 36936987, 2023). "ITGB1 expression was observed in 42.9% (21/49) of T1‐stage cancers, 63.0% (34/54) of T2‐stage cancers, and 64.0% (203/317) of T3 + T4‐stage cancers." (PMID 35864742, 2023). "ITGB1 functions as an oncogene in different types of human cancers 38, 39 and the overexpression of ITGB1 is found to promote the growth and metastasis of HCC cells." (PMID 35371321, 2022). "Since the impact of ITGB1 in cancer progression is controversial, we firstly studied the clinical relevance of ITGB1 in PrCa." (PMID 35202085, 2022). "CD44/ITGB1 based sorting of the A431 cell line also identified a subset within the cancer stem cells (CSC) that display EMT characteristics." (PMID 35666359, 2022). "The presented study confirmed the sarcoid-specific increase in the expression of not only the JAM3 gene, but also the ITGB1 gene, whose expression is considered to be a poor outcome marker during cancer prognosis." (PMID 35742950, 2022). "Consistently, the gene expression of collagen I receptors, linked to active tissue remodeling and cancer, including DDR2, ITGA2, ITGA10, ITGA11 and ITGB1 was higher in OS compared to RMS, whilst DDR1 expression was higher in RMS tumors." (PMID 35957513, 2022). "Findings in other studies had proposed that up-regulation of ITGB1 would contribute to cell survival after radiation exposure in various cancers, thus facilitating resistance." (PMID 36456612, 2022).
cancer (continued). "TIMP-1 has been reported to act in a growth-stimulatory manner on many cancer cells, including BC cells, and CD63 and ITGB1 were linked to drug resistance of BC cells." (PMID 36291767, 2022). "We evaluated the expression of ITGB1, a factor that has been reported to contribute to the infiltration and metastasis of various carcinomas." (PMID 35648752, 2022). "Taken together, these results demonstrate that TFEB-induced ITGB1 degradation can restrain the mobility of cancer cells in part via the CTSL mediated lysosomal degradation." (PMID 33803301, 2021). "Functional assays using siRNAs demonstrated that knockdown of ITGA6 and ITGB1 suppressed cancer cell malignant phenotypes, especially cell migration and invasive abilities." (PMID 34199886, 2021). "Integrin ITGB1 promotes cell invasion by sensitizing cancer cells to the changes in the fibrotic stroma, while Rho-GTPases are indispensable in the regulation of cell migration and control of multiple aspects of M phase and G1 progression of the cell cycle." (PMID 34458147, 2021). "Alteration of integrin β1(ITGB1) spatial distribution and temporal expression have been frequently observed in multiple cancers including HCC." (PMID 33803301, 2021). "Previous studies showed that several miRNAs (e.g., miR-29, miR-124-3p, miR-150, miR-218 and miR-199) directly controlled expression of ITGA6 and ITGB1 in several cancers." (PMID 34199886, 2021). "ITGB1 is a member of the integrin family, beneficial to survival, differentiation, angiogenesis, and invasion of cancer cells mediated by the interaction between cells and extracellular matrix." (PMID 33014056, 2020). "This is in contrast to studies in which ITGA2 and ITGB1 have been found to suppress metastasis in models of mouse and human cancer." (PMID 33276802, 2020). "Integrin beta 1 subunit (ITGB1), together with multiple integrin alpha subunits, can interact with pleiotropic ligands and promote cancer cell proliferation and metastasis." (PMID 33277616, 2020). "Our results consistent with these reports and indicated that SPP1 has a more important correlation with CD44 and ITGB1 in selected cancer contrast to adjacent normal tissue." (PMID 33324676, 2020). "ITGA2 forms a homodimer with ITGB1, and dysregulated levels of ITGA2/ITGB1 can mediate the signal pathways that enhance malignant transformation in multiple types of cancer cells." (PMID 32899691, 2020). "ITGB1, Integrin Subunit Beta 1, encodes protein CD29 and plays an important role in cancer cell motility, survival, and attachment." (PMID 31217907, 2019). "Previous studies showed that MARVELD1 mediated the balance between ITGB1 and ITGB4 in cancer cells through down-regulating the expression of ITGB1 in mRNA processing and up-regulating ITGB4 by binding its promoter." (PMID 30250269, 2018). "Knockdown of ITGB1 significantly inhibited cancer cell migration and invasion through regulating downstream of ITGB1-mediated oncogenic signalling." (PMID 29423074, 2018). "ITGB1 was quantitatively controlled by miR-29a in cancer cells and astonishingly, TERT negatively regulated miR-29a expression." (PMID 29614790, 2018). "Overexpression of ITGB1 was frequently observed several cancers, including HNSCC, resulting in activation of ITGB1-mediated downstream signalling pathways." (PMID 29423074, 2018). "Increasing knowledge of ITGB1 suggests that aberrant expression and activation of ITGB1-mediated cancer signalling is involved in cancer cell aggressiveness." (PMID 29423074, 2018). "FERMT2 readily binds ITGB1 cytoplasmic domains and has also been reported to be highly expressed within cancers where it promotes migration and invasion." (PMID 30382829, 2018). "Laminin-332 can interact with two types of integrins, ITGA6/ITGB4 (α6β4) and ITGA3/ITGB1 (α3β1), and activation of laminin-332-mediated integrin signalling enhances cancer cell development and metastasis." (PMID 29423074, 2018).
cancer (continued). "SCAI was previously shown to suppress cancer cell invasion through transcriptional regulation of integrin β1 (ITGB1)." (PMID 28423650, 2017). "The proteins ITGA3 and ITGB1 were abundant in cancer cell exosomes and in the secretome of metastatic cell lines." (PMID 24371517, 2013). "Notably, genes including CAV1, ITGB1, BNIP3, and YTHDF2 were associated with the AKT signalling pathway, suggesting a functional link between ODC1 activity and cancer progression." (PMID 41803527, 2026). "The pathway enriched in “Pathways in Cancer” with 15 genes, including ITGB1, STAT5A, and EGF." (PMID 40621499, 2025). "Integrin β1 (ITGB1) functions as a GC receptor in both cancer cells and Schwann cells." (PMID 40923379, 2025). "COL1A1 supports ITGB1 and many other molecules in the invasion and migration of cancer cells." (PMID 38963646, 2025). "Additionally, ITGB1 is highly expressed in various cancer tissues, where it promotes cancer metastasis and spread 34-36." (PMID 40585991, 2025). "The “Pathways in Cancer” involve ITGB1, NOTCH2, and HSP90AB1 genes." (PMID 40621499, 2025). "“Pathways in cancer” pathway, represented by genes ITGB1, STAT5A, and EGF." (PMID 40621499, 2025). "Loss of expression of either Kindlin-2, TβRI or ITGB1 resulted in the inability of the MDA-MB-231-KO cells or the 4T1 KO cells to effectively close the scratch wound after 24 h, supporting the role of Kindlin-2, TβRI and β1-Integrin in cancer cell migration." (PMID 39300257, 2024). "A thorough examination of ITGB1's functions in human malignancies, however, is inadequate and many of their relationships to the onset and development of human cancers remain unknown." (PMID 38402311, 2024). "Studies have found that "Cell adhesion" and "Protein binding" may be involved in the role of ITGB1 in cancer pathogenesis." (PMID 38402311, 2024). "In summary, these findings showed that CAFs and cancer cells may communicate with one another due to integrin-mediated ECM remodeling in the TME, thereby supporting the progression and metastasis of cancer, and ITGB1 is involved in important processes." (PMID 38279122, 2024). "We looked into ITGB1's prognostic importance in 33 distinct cancer types in further detail." (PMID 38402311, 2024). "ITGB1 plays an essential role in metastasis as well, but there are variations therein, implying that the background to cancer may be relevant to the downstream pathways targeted by ITGB1." (PMID 38279122, 2024). "This study looked into the expression of ITGB1 in 33 cancers from the TCGA database." (PMID 38402311, 2024). "Furthermore, it is demonstrated that when ITGB1 is overexpressed and overactivated in cancer, such as in lung, colorectal, pancreatic and breast carcinoma it is also associated with a poor prognosis." (PMID 38177190, 2024). "Finally, the intersection of the two up-regulated cancer types revealed that ITGB1 expression was up-regulated in ESCA, STAD, and HNSC." (PMID 38402311, 2024). "This suggests that ITGB1 has an important role in controlling cancer metastasis and proliferation." (PMID 38582791, 2024). "In the gene co-expression research, ITGB1 showed a positive connection with the majority of the cell proliferation and EMT indicators, indicating that ITGB1 may have an essential function in controlling cancer metastasis and proliferation." (PMID 38402311, 2024). "We investigated ITGB1 gene alterations in the TCGA cancer profiling study using cBioPortal." (PMID 38402311, 2024). "To further test how ITGB1 affects IGF-1R activity, we asked whether ITGB1 influences IGF-1R subcellular location in actively adhering cancer cells." (PMID 39608716, 2024). "In addition, it was discovered through survival analysis that ITGB1 was a stand-alone prognostic factor in a number of cancers." (PMID 38402311, 2024).
cancer (continued). "In this study, we found that ITGB1 CAFs are expressed in the 18 types of cancer are related (in four kinds of algorithms are all p < 0.05), suggesting that ITGB1 is likely to be involved in the conversion of CAFs and activation, and promote the development of cancer." (PMID 38402311, 2024). "Furthermore, if their levels surpass a certain threshold, such as in cancer, Itgb1 levels rise, which is advantageous for invading cancer cells." (PMID 39506038, 2024). "Cell experiments verified that knockdown of ITGB1 in CaSki and HeLa cells could significantly inhibit cancer cell proliferation, migration, and invasion abilities." (PMID 37449209, 2023). "Furthermore, myeloid cells can transmit cancer-promoting signals to MFAP5 + fibroblasts via the NAMPT-ITGA5/ITGB1 pair (VISFATIN signaling pathway)." (PMID 37344903, 2023). "ITGB1 has been reported to regulate cancer migration, invasion, and metastasis." (PMID 38248716, 2023). "We reported in a previous study that LP could bind to integrin beta 1 (ITGB1) receptors overexpressed in various cancer cells." (PMID 37598155, 2023). "In addition, macrophages and endothelial cells secreted large numbers of cytokines which interacted with SDC1, SDC4, and ITGB1 in cancer cells." (PMID 34745098, 2021). "Expression of ITGA6 and ITGB1 was detected in the cancer cells." (PMID 34199886, 2021). "Moreover, overexpression of miR-124-3p inhibited ITGA3/ITGB1-mediated oncogenic signaling, and attenuated cancer cell migration and invasive abilities." (PMID 34199886, 2021). "Cellular TFEB, through activation of autolysosome flux and induction of CTSL, could induce ITGB1 degradation, which consequently suppressed the cancer cell migration." (PMID 33803301, 2021). "Overexpression of both ITGA2 and ITGB1 was detected in these cancer lesions." (PMID 32899691, 2020). "miR-29c has been investigated in a number of cancer settings with a number of confirmed targets identified, including integrin beta 1 (ITGB1) and matrix metalloproteinase 2 (MMP2) for which luciferase reporter assays confirming direct targeting of miR-29c has been previously reported." (PMID 31201347, 2019). "ITGB1 plays critical roles in the maintenance of cell proliferation and movement, evidenced by the finding that the over-expression of ITGB1 genes could increase cancer cell proliferation and metastasis which was declined by deletion of ITGB1 gene." (PMID 31888636, 2019). "Our previous studies showed that F806 suppresses cancer progression; though it downregulates the protein expression of actin cytoskeleton linkers ITGB1 and GRB2, proteins are involved in the formation of focal adhesions, which implies F806 can control dynamic changes of the cytoskeleton." (PMID 30327774, 2018). "Cancer cell migration and invasion abilities were enhanced by overexpression of ITGB1 in SAS cells." (PMID 29423074, 2018). "Integrin β1 (ITGB1) was significantly increased in TERT over-expressing SGC7901 cancer cells." (PMID 29614790, 2018). "Moreover, ectopic expression of the miR-29 family and knockdown of ITGB1 suppressed cancer cell aggressiveness by inhibiting ITGB1-mediated downstream signalling." (PMID 29423074, 2018). "Overexpression of ITGB1 has been frequently observed in several cancers, including PDAC." (PMID 29988949, 2018). "Importantly, also the mean expression of ITGB1 was higher in the cancer areas (215%; p < 0.001, Welch ́s one-way ANOVA)." (PMID 29402961, 2018). "Inhibition of ITGB1 significantly reduced cancer cell aggressiveness, indicating that ITGB1 and ITGB1-mediated cancer signalling may be promising therapeutic targets for HNSCC." (PMID 29423074, 2018). "Therefore, inhibition of ITGB1 and ITGB1-mediated cancer signalling is attractive as a new treatment strategy for cancer cells that have acquired treatment resistance." (PMID 29423074, 2018).
cancer (continued). "Similarly, ITGB1, a cell adhesive molecule, which functions to mediate association between cells and the ECM, has also been found to be misregulated in various cancers and found to impact malignant phenotypes such as invasion, proliferation and angiogenesis." (PMID 28378523, 2017). "Here, ITGB1 was upregulated by both cancer cell types in response to confining matrix conditions." (PMID 29162797, 2017). "lncRNA-H19 and circular MYLK as well as circular CTDP1 could regulate the expression of DNMT3B, HAS3, VEGFA and ITGB1 through competing miRNA response elements (MREs) of miRNA-29a-3p, which would result in growth and metastasis of cancer." (PMID 27363013, 2016). "In line with miR-223 function are the evidences that integrins, in particular ITGA3 and ITGB1, are key mediators of the outside-in and inside-out signalling in cancer and their depletion leads to decreased migratory abilities and inhibition of metastasis formation." (PMID 24400121, 2014). "Additionally, SPP1 as a ligand could induce communications of pan T‐cell subtypes to cancer cells specifically in BM or to senescent cancer cells via adhesive receptors ITGAV_ITGB1, ITGAV_ITGB5 and ITGAV_ITGB6." (PMID 39231761, 2025). "Additionally, the interactions through the SPP1‐CD44 and SPP1‐ITGA4_ITGB1 pairs between cancer cells and T cells occurred more frequently in BM than in PT and were also more prevalent in senescence‐positive cancer cells compared to senescence‐negative counterparts." (PMID 39231761, 2025). "Similarly, mutations in ITGB1, ITGB3, and ITGB7 can alter their interaction with calpain, which may affect the focal adhesion of cancer cells and therefore needs to be validated further via a multidisciplinary approach." (PMID 40362482, 2025). "Furthermore, loss of ITGB1 stabilizes IGF-1R protein levels, which may indicate that ITGB1 is required for IGF-1R protein turnover in migratory cancer cells." (PMID 39608716, 2024). "We propose that intracellular IGF-1R may serve as a putative biomarker for aggressive cancers, and that therapeutic approaches targeting both ITGB1 and IGF-1R may increase IGF-1R cell surface presence to enhance therapeutic efficacy of cell surface-targeted anti-IGF-1R monoclonal antibodies." (PMID 39608716, 2024). "Importantly, previous studies suggested that ITGB1 may be an enhancer maintaining resistance to cancer chemotherapy." (PMID 38737262, 2024). "Importantly, our unbiased analysis of existing public database revealed a statistically significant positive correlation between USP22 and ITGB1 in 37 total human cancer types, suggesting that the USP22-FoxM1-integrin b1 axis is a common mechanism in CSC self-renewal." (PMID 37398311, 2023). "Furthermore, FLT1 of LUSC, ITGB1 of DLBC, MDM4, and CDKN1A of ACC, MAPK1, and ERBB3 of UCEC, FGFR1 of ESCA, and EREG and BCL2L1 of COAD have been strongly associated with patient survival in their respective cancers." (PMID 34079798, 2021). "Most of the genes in the 9-gene classifier (ITGB1, EPHA2, IL1R2) are involved in the migration, immune pathways, adhesion and metastasis of PDAC or other cancers, that are specifically associated with the developmental events and signaling in the progression of cancer." (PMID 33133160, 2020). "Moreover, integrin α3 (ITGA3) and β1 (ITGB1), heterodimeric transmembrane receptors, were also overexpressed in naïve PCa clinical specimens, and integrin‐mediated oncogenic signaling enhanced cancer cell aggressiveness." (PMID 29608247, 2018). "Moreover, activation of ITGB1-mediated signals enhances chemoresistance in several cancers." (PMID 29423074, 2018). "The remaining nine surface proteins identified solely (ANTXR1, AG1, DCBLD2, EFNB1, EMB, OSMR, SLC1A5) or found upregulated (ATP1B3 and ITGB1) on the MCF10A surface had no direct association with embryonic development signaling in the context of KRas mutant signaling in cancer cell lines." (PMID 27894102, 2016).